RER1 (retention in endoplasmic reticulum sorting receptor 1)
Description:
Involved in the retention or retrieval of proteins localized in the endoplasmic reticulum from the early Golgi compartment, including the gamma-secretase complex subunit PEN-2 (PSENEN). Regulates intracellular trafficking of the gamma-secretase complex and amyloid-beta precursor protein (APP), thereby controlling APP levels at the cell surface and influencing the release of amyloid-beta peptides generated through gamma-secretase mediated processing of APP. During cerebral cortex and neural stem cell development, it is required to maintain sufficient expression and activity of gamma-secretase complex at the cell surface, modulating NOTCH processing and signaling (By similarity). In addition to its role in the control of protein trafficking, the RER1-dependent Golgi apparatus-endoplasmic reticulum retrieval system may regulate proteasomal degradation of alpha-synuclein (SNCA).
Tractability: Antibody: UniProt predicts a signal peptide or a membrane-spanning region; its Gene Ontology location is reachable by antibodies, with medium confidence. PROTAC: ubiquitination databases record sites on it; its protein half-life has been measured.
Gene: Protein-coding gene on chromosome 1 (2,390,670 to 2,405,444, forward strand). Ensembl gene ENSG00000157916.
Subcellular location: Golgi apparatus membrane; Golgi apparatus, cis-Golgi network membrane
Subcellular location (Human Protein Atlas): Golgi apparatus
Gene Ontology:
Molecular function: protein binding; acetylcholine receptor binding
Biological process: maintenance of protein localization in endoplasmic reticulum; retrograde vesicle-mediated transport, Golgi to endoplasmic reticulum; protein retention in ER lumen
Cellular component: cis-Golgi network; Golgi apparatus; Golgi membrane; cell surface; cytoplasm; endoplasmic reticulum; endoplasmic reticulum-Golgi intermediate compartment; membrane
Genetic constraint (gnomAD): Loss-of-function variants: 5 observed, 16.55 expected, observed/expected ratio (o/e) 0.3, 90% interval 0.16 to 0.63. The upper end of that interval is the gene's LOEUF score, 0.63, which puts it in group 2 of 6, group 1 being the genes least tolerant of losing a copy. Missense variants: 120 observed, 207.54 expected, observed/expected ratio (o/e) 0.58, 90% interval 0.5 to 0.67. Synonymous variants: 92 observed, 81.96 expected, observed/expected ratio (o/e) 1.12, 90% interval 0.95 to 1.34.
Homologues: Orthologues: chimpanzee RER1 (99% identical), guinea pig RER1 (97% identical), dog RER1 (96% identical), mouse Rer1 (96% identical), rat Rer1 (96% identical), pig RER1 (94% identical), macaque RER1 (93% identical), tropical clawed frog rer1 (91% identical), zebrafish rer1 (84% identical), rabbit RER1 (82% identical), Drosophila melanogaster CG11857 (60% identical), Caenorhabditis elegans rer-1 (57% identical).
Diseases named in the same sentence as RER1 in open-access papers:
RER1 is named in the same sentence as 22 diseases in open-access papers, as found by Europe PMC text mining. Sharing a sentence is not in itself a finding about the gene and the disease. The quoted sentences say what the papers report.
pancreatic cancer (7 papers, 2019 to 2024). "RER1 enhances carcinogenesis and the stemness of pancreatic cancer under the hypoxic environment, which is associated with hepatocellular carcinoma." (PMID 32596394, 2020). "Additionally, several proteins that drove diseases such as RER1 enhancing carcinogenesis and stemness of pancreatic cancer and Igfbp1 confirmed as stroke risk marker were also increased in liver after caffeine administration." (PMID 38188177, 2024). "Interestingly, the RER1 gene has been associated with colon and pancreatic cancer." (PMID 39595158, 2024). "Yet, RER1 has been found to be upregulated in pancreatic cancer and also in liver cancer in our findings." (PMID 31640796, 2019). "The functional effect of RER1 has only been reported in human cancers in terms of its capacity to promote epithelial-mesenchymal-transition, stemness of cancer stem cells, tumorigenesis and metastasis in pancreatic cancer." (PMID 31640796, 2019). "Interestingly, besides Myc, Rer1 levels are also found to be high in pancreatic cancer cells." (PMID 38408084, 2024). "Additionally, genes coexpressed with GNG5, such as AK2, are highly expressed in lung cancer and can lead to poor prognosis in patients; besides, RER1 as a coexpressed gene with GNG5, could promote the progression of pancreatic cancer and reduce the survival rate of patients." (PMID 34098960, 2021).
glioma (2 papers, 2022 to 2023). A benign or malignant brain and spinal cord tumor that arises from glial cells (astrocytes, oligodendrocytes, ependymal cells). "we found that SAMD8, RER1, MXI1, and CHI3L1 were highly expressed in most of the glioma tumor microenvironment cells." (PMID 37934565, 2023). "Human-cultured neuroblastoma SH-SY5Y and glioma U251 cells, with endogenous expression of both NEDD4-2 and RER1, were used to investigate the NEDD4-2-mediated ubiquitination of RER1 in vitro." (PMID 35832397, 2022).
Parkinson disease (2 papers, 2017 to 2019). A progressive degenerative disorder of the central nervous system characterized by loss of dopamine producing neurons in the substantia nigra and the presence of Lewy bodies in the substantia nigra and locus coeruleus. "Recent studies have revealed that RER1 may be also related to abnormal accumulation of α-synuclein in the ER, which is a critical mechanism of Parkinson disease." (PMID 30630537, 2019). "Further investigation of the mechanism of RER1 and downstream effectors on αSyn may yield novel therapeutic targets for modulation in Parkinson disease and related synucleinopathies." (PMID 28877262, 2017).
Alzheimer disease (1 paper, 2017). A progressive, neurodegenerative disease characterized by loss of function and death of nerve cells in several areas of the brain leading to loss of cognitive function such as memory and language. "Recently retention in endoplasmic reticulum 1 (RER1) has been identified as an important ER retrieval/retention factor for Alzheimer’s disease proteins and negatively regulates amyloid-β peptide levels." (PMID 28877262, 2017). "Recently, we and other groups have identified human Retention in endoplasmic reticulum 1 (RER1) as an important protein that mediates ER-Golgi trafficking of Alzheimer’s disease (AD)-related proteins and significantly decreases amyloid-β (Aβ) production." (PMID 28877262, 2017).
Anxiety (1 paper, 2018). Intense feelings of nervousness, tension, or panic often arise in response to interpersonal stresses. "Interestingly, forebrain-specific Rer1 cKO mice spent more time than control mice around the center of the field, suggesting that Rer1 loss in the forebrain reduces anxiety." (PMID 30260951, 2018). "We also examined anxiety and general locomotor activity levels of Rer1 cKO mice via the open field test." (PMID 30260951, 2018).
behavioral disorder (1 paper, 2018). "Notably, Rer1 loss in the cerebral cortex resulted in cerebral hypoplasia and behavioral disorder, which recapitulates the brain defects present in most patients with 1p36-deletion syndrome, suggesting that Rer1 mutations are one of the causative factors for this syndrome." (PMID 30260951, 2018).
Charcot-Marie-Tooth disease (1 paper, 2019). An inherited degenerative disorder involving the peripheral nerves. "A previous study reported that Charcot-Marie-Tooth disease was related to the retention of a peripheral myelin protein 22 (PMP22) mutant regulated by RER1 and calnexin." (PMID 30630537, 2019).
Dementia with (1 paper, 2017). "In this study, we examined the distribution of RER1 in healthy human control and LB-positive disease brains (from Dementia with Lewy body cases) using an affinity purified RER1 antibody (AP-R76)." (PMID 28877262, 2017).
epilepsy (1 paper, 2022). A brain disorder characterized by episodes of abnormally increased neuronal discharge resulting in transient episodes of sensory or motor neurological dysfunction, or psychic dysfunction. "It is not known whether RER1 is implicated in epilepsy through some transmembrane ion channels or neurotransmitter receptors." (PMID 35832397, 2022). "RER1 might likely be involved in epilepsy through ER retention of cerebral ion channels." (PMID 35832397, 2022).
Lewy body disease (1 paper, 2017). "In this study we examine the effect of RER1 expression on αSyn in human and neuronal cell lines, and its expression pattern in Lewy body disease tissue." (PMID 28877262, 2017). "We demonstrate also that RER1 accumulates and colocalizes with LBs in human DLB (dementia with Lewy body) brain tissue." (PMID 28877262, 2017).
cancer (7 papers, 2019 to 2025). A tumor composed of atypical neoplastic, often pleomorphic cells that invade other tissues. "A recent study reported RER1 as one of the newly identified reference genes for quantifying cancer-related gene expression level." (PMID 31640796, 2019). "Thus, further studies on the effect of Rer1 in Myc-induced overgrowth will be helpful in developing Rer1 as a potential therapeutic target in Myc-driven cancers." (PMID 38408084, 2024). "RER1 has not been well characterized for its role in human cancers." (PMID 31640796, 2019). "However, no previous study has demonstrated the function of RER1 in cancer." (PMID 30630537, 2019). "Expression of other members of RQC including Pelota, SMG1 did not correlate across cancer types, nor were patterns observed in the expression of reference genes (GAPDH, HNRPL, PCBP1, SNW1, and RER1) identified to have stable expression patterns in human cancer and matching normal cell types." (PMID 38140537, 2023).
tumor (5 papers, 2019 to 2024). "We pooled all 20 genes (Stx6, Ramp1, Traf3ip1, Nckap5, Pfkfb2, Trmt1l, Rprd1b, Rer1, Sepsecs, Rhobtb1, Tsen15, Abcc3, Arid5b, Tnr, Dock2, Tti1, Fam81a, Oxr1, Plxna2 and Tbc1d31) together as the mouse tumour susceptibility gene signature (mTSGS)." (PMID 39067134, 2024). "Multivariate Cox regression analysis identified SNPs in 8 genes (Stx6, Ramp1, Traf3ip1, Nckap5, Pfkfb2, Trmt1l, Rprd1b, and Rer1) that were independently associated with age of tumour onset." (PMID 39067134, 2024). "RER1 knockdown significantly repressed PC cell proliferation, migration, aggressiveness and tumor formation." (PMID 30630537, 2019). "The mRNA levels of RER1 in the 50 PC tissues and 15 adjacent normal tissues were determined by qRT-PCR, which demonstrated a significantly higher RER1 mRNA level in tumor tissues than adjacent tissues." (PMID 30630537, 2019). "When the same number of cells were injected, RER1-overexpressing PANC-1 cells showed higher tumor incidence rate than control cells, indicating RER1 was able to enhance tumorigenesis of PANC-1 cells." (PMID 30630537, 2019). "By analyzing 45 matching pairs of PC from GSE28735, higher Rer1 expression level was shown in tumor compared to adjacent tissues." (PMID 30630537, 2019). "After confirming the positive role of RER1 in cell proliferation, we implanted PANC-1-pSin-vec and PANC-1-pSin-RER1 cells in to the flanks of male nude mice, and observed that RER1 overexpression markedly promoted tumor growth." (PMID 30630537, 2019). "In the case of RER1, AS events in this gene ranked in the top 5 in 9 out of 16 tumor types." (PMID 39595158, 2024). "Multivariate analyses flagged SNPs in 20 genes (Stx6, Ramp1, Traf3ip1, Nckap5, Pfkfb2, Trmt1l, Rprd1b, Rer1, Sepsecs, Rhobtb1, Tsen15, Abcc3, Arid5b, Tnr, Dock2, Tti1, Fam81a, Oxr1, Plxna2, and Tbc1d31) independently tied to various tumour characteristics, designated as a mTSGS." (PMID 39067134, 2024). "Tumor formation was also significantly repressed in RER1 knockdown cells compared to control." (PMID 30630537, 2019). "RER1 expression levels were higher in PC tumor tissues than adjacent normal tissues, indicating RER1 may play a positive role in PC progression." (PMID 30630537, 2019). "For example, BCL9L, P2RX6, RER1, EFNA2, CASK, CERCAM, and PTPRN were demonstrated to promote EMT, metastasis, and invasion of tumor cells." (PMID 35586092, 2022). "Cell proliferation, colony formation, tumor formation, scratch test, and transwell invasion assays were performed in RER1 knockdown cells and negative control cells." (PMID 30630537, 2019). "Because we identified that RER1 is capable of inducing stemness of PC cells, it is also possible that RER1 overexpression elicits the conversion of PC cells to CSCs, which undergo EMT to generate circulating tumor cells." (PMID 30630537, 2019).
RER1 also shares sentences with these, for which no sentence is quoted: atherosclerosis (1 paper); diabetes (1); hepatocellular carcinoma (1); liver cancer (1); lung carcinoma (1); neuroblastoma (1); Obesity (1); Seizure (1); Stroke (1); synucleinopathies (1).